MIR300 (microRNA 300)
Synonyms: hsa-mir-300; MIRN300
Gene: MicroRNA gene on chromosome 14 (101,041,363 to 101,041,445, forward strand). Ensembl gene ENSG00000215957.
Gene Ontology:
Biological process: miRNA-mediated post-transcriptional gene silencing
Cellular component: RISC complex